TNF (tumor necrosis factor)
Diseases named in the same sentence as TNF in open-access papers (continued):
Sharing a sentence is not in itself a finding about the gene and the disease.
mental disorder (22 papers, 2013 to 2025). A disease that has its basis in the disruption of mental process. "However, accumulating evidence suggests that mental disorders are associated with elevated levels of inflammatory biomarkers, such as interleukin-6 (IL-6), tumor necrosis factor-alpha (TNF-α), and C-reactive protein (CRP)." (PMID 41019538, 2025). "The biological activities and functions of TNF-α have been described in different pathological processes in humans and mammals, including neoplastic diseases, mental disorders and inflammation-mediated biological defense functions." (PMID 36593850, 2022). "Subsequently, we examined how immune-mediated classes were reflected in leukocyte counts, inflammatory markers (IL-1β, IL-6, TNF-α, hsCRP), chronic inflammatory diseases, and mental disorders, and how they differed across social classes and birth cohorts." (PMID 30961604, 2019). "On the other hand, S100-βactivates inflammatory pathways, stimulating microglia and astrocytes to releasepro-inflammatory cytokines, such as tumor necrosis factor-α(TNF-α) and interleukin-1β (IL-1β), further exacerbatingneuroinflammation and contributing to the onset of mental disorders." (PMID 39801405, 2025). "Compared to common cytokines like INF-γ, IL-6, and TNF-a, NLRP3 and IL-18 have rarely been studied in clinical studies of mental disorders." (PMID 38627683, 2024). "The population taking TNF‐α inhibitors included in this review, instead, had no prior history of mental disorders." (PMID 34590391, 2022). "In this systematic review, we sought to analyze the available evidence on the putative role of TNF‐α in triggering hypomanic or manic episodes in patients with or without a mental disorder." (PMID 34590391, 2022). "A meta-analysis also suggested IL-6 and TNF-α may play a negative role in the pathogenesis of mental disorders." (PMID 36465283, 2022).
pneumococcal meningitis (22 papers, 2007 to 2025). An acute purulent infection of the meninges and subarachnoid space caused by Streptococcus pneumoniae, most prevalent in children and adults over the age of 60. "TNF-α-deficient mice showed increased mortality and stronger deficits in spatial memory possibly due to impaired neurogenesis after pneumococcal meningitis." (PMID 27057100, 2016). "We also measured CSF IL-1β, TNF-α, IL-10 and IL-17A concentrations in 402 patients with pneumococcal meningitis (Appendix p9)." (PMID 41161094, 2025). "TNF, a proinflammatory family, can be activated in intracephalic inflammation based on cytokine stress induced by pneumococcal meningitis, such as TNF-α and IL-1β." (PMID 33031061, 2020). "Next, gene expression levels of the pro-inflammatory cytokines TNF-α or IL-6 as major mediators of the inflammatory reaction during pneumococcal meningitis were determined in the hippocampal formation as well as cortex 28 h after infection." (PMID 33121515, 2020). "In situ hybridization studies have shown that in murine pneumococcal meningitis, TNF-a mRNA is first upregulated in astroglial cells but is strongly increased in hippocampal neurons at 18–24 h." (PMID 32087723, 2020). "TNF-α, IL-1β, and IL-6 are the major pro-inflammatory cytokines with early response in pneumococcal meningitis." (PMID 32238192, 2020). "TNF-a and IL-1b are expressed in hippocampal neurons in vivo in response to lesions and pneumococcal meningitis." (PMID 32087723, 2020). "In situ hybridization studies show that in murine pneumococcal meningitis IL-1β and TNF-a mRNA were first upregulated in astroglial cells but at 18–24 h were strongly increased in hippocampal neurons." (PMID 30858801, 2019). "According to our data, BPI correlates with pro-inflammatory markers like TNFα in CSF of patients with pneumococcal meningitis." (PMID 30581431, 2018). "At first, we examined the gene expression of the proinflammatory cytokines TNF-α, IL-6, and IL-1β as representatives of inflammatory mediators in pneumococcal meningitis." (PMID 27057100, 2016). "In situ hybridization studies show that in murine pneumococcal meningitis TNF-a mRNA was first upregulated in astroglial cells but at 18–24 h was strongly increased in hippocampal neurons." (PMID 27853420, 2016). "In situ hybridisation for TNF-α mRNA has been detected in GFAP-positive astrocytes in mice suffering from pneumococcal meningitis which also suggests that astrocytes can indeed produce TNF-α in CNS pathologies." (PMID 26988764, 2016). "Our previous studies showed an increased expression of the proinflammatory cytokines TNF-α and IL-6 in CRAMP-deficient mice after pneumococcal meningitis." (PMID 27057100, 2016). "IL-8 appears to regulate CSF pleocytosis in pneumococcal meningitis from the systemic compartment, similar to that seen for TNF, IL-10, and TGF-β." (PMID 23997430, 2013). "The anti-inflammatory cytokine IL-10 has been implicated in playing a role in modulating the immune response by downregulating TNF, IL-6, and keratinocyte-derived chemokine (KC), thereby reducing CSF pleocytosis in pneumococcal meningitis." (PMID 23997430, 2013). "TNF-α, IL-1 and IL-6 are considered to be the early response proinflammatory cytokines that are upregulated early in during pneumococcal meningitis." (PMID 22455545, 2012). "In addition, IL-1 and TNF-α are induced during murine pneumococcal disease and elevated levels of both have been reported in patients with pneumococcal meningitis." (PMID 21085613, 2010). "However, pharmacological downregulation of TNF-α levels in the CSF decreased mortality and neuronal damage and improved the learning performance 3 weeks after infection in a rat model of pneumococcal meningitis providing evidence for better outcome by reducing TNF-α levels." (PMID 27057100, 2016).
pneumococcal meningitis (continued). "Whereas, in experimental pneumococcal meningitis model the animals presented, in the first twenty four hours, elevated levels of TNF-α and CINC-1 in the hippocampus and TNF-α, IL-1β, IL-6 and CINC-1 in frontal cortex." (PMID 23548182, 2013). "In this respect, TNF and matrix-metalloproteases (MMPs) are major therapeutic targets since both molecules are up-regulated early; TNF levels in CSF are related to disease severity and TNF and MMP's contribute to brain injury during pneumococcal meningitis." (PMID 17428319, 2007). "Based on our earlier studies with TACE inhibitor TNF484 in neonatal rat pneumococcal meningitis, we first confirmed that TNF484 used at 1 mg/kg twice daily blocked TNF and MMP-9 in CSF of infected mice." (PMID 17428319, 2007). "IL-1β, IL-2, IL-4, IL-10, IL-12p70, IL-17, RANTES, TNF-α, IL-18 and IL-33 were not significantly altered in the plasma of mice with pneumococcal meningitis compared to sham controls." (PMID 22455545, 2012). "IL-2, IL-4, IL-10, IL-12p70, IL-17, IFN-γ, TNF-α, IL-18 and IL-33 were not altered in brain homogenates of mice with pneumococcal meningitis compared to sham controls." (PMID 22455545, 2012). "In pneumococcal meningitis, we found a shorter survival in CD14-/- than in wt mice, which was due to enhanced CXCR2 expression leading to early recruitment of leukocyte and increased TNF in cerebrospinal fluid (CSF)." (PMID 17428319, 2007).
post-traumatic stress disorder (22 papers, 2012 to 2025). An anxiety disorder precipitated by an experience of intense fear or horror while exposed to a traumatic (especially life-threatening) event. "From 2001 to 2020, burst strength was the highest for neuroinflammation (7.6649), followed by septic encephalopathy (6.4582), blood-brain barrier (5.9004), TNF (5.83), post-traumatic stress disorder (4.8628), and SAE (4.4181)." (PMID 35295600, 2022). "In addition, the post-traumatic stress disorder (PTSD) is associated with increased levels of IL-6, interleukin-1 beta (IL-1β), interferon gamma (INFγ) and tumor necrosis factor alpha (TNFα)." (PMID 32858844, 2020). "Furthermore, posttraumatic stress disorder was found to cause upregulation of serum interleukin 6 (IL-6) and proinflammatory cytokines, such as interferon-gamma (IFN-γ), interleukin 1 β (IL-1β), interleukin 10 (IL 10), and tumor necrosis factor α (TNF α)." (PMID 34966477, 2021). "In animal models of post-traumatic stress disorder (PTSD), S-ketamine has been shown to attenuate pro-inflammatory responses by reducing TNF-α and IL-1β levels in critical brain regions such as the striatum and periaqueductal gray." (PMID 41369360, 2025). "Methylation of the AIM2 gene at the site cg10636246 drives the relationship between trauma exposure, posttraumatic stress disorder (PTSD), the level of C-reactive protein (CRP) and other inflammatory mediators, such as IL-6, IL-10, and TNF-α, in the body." (PMID 36742336, 2023). "Furthermore, post-traumatic stress disorder (PTSD) is also characterized by inflammation dysregulation, determining changes in the levels of IL-6 and TNF-α." (PMID 39458125, 2024).
tetanus (22 papers, 2006 to 2025). A serious infectious disorder that follows wound contamination by the Gram-positive bacterium Clostridium tetani. "Tetanus also stimulated a substantial population of Tbet- IL-2- IFNγ- TNFα+ cells, consistent with stochastic expression of IL-2 in the Thpp as well as the Th1 population." (PMID 24788814, 2014). "Levels of TNF-α showed similar median plasma concentrations in both periods, i.e. 4.5 (range -2.7–6.7) pg/ml and 4.1 (range -1.2–6.8) pg/ml in autonomic instability and after tetanus recovery, respectively p > 0.05." (PMID 16503969, 2006). "The objective of the present study was to evaluate the temporal behavior of catecholamines and of TNF-α relative to left ventricular ejection fraction obtained by two-dimensional transthoracic echocardiography at two time points: during autonomic instability and after recovery from tetanus." (PMID 16503969, 2006). "Since it is well known that myocardial damage caused by catecholamines can induce synthesis of cytokines by myocytes, cytokines, specifically those with known cardiodepressant properties such as TNF-α, could be an alternative mechanism involved in cardiac dysfunction, in the setting of tetanus." (PMID 16503969, 2006). "T cell activation was assessed by measurement of intracellular cytokines (IL-2, IFNγ, TNFα) following stimulation of peripheral blood T cells with PHA, a tetanus and diphtheria cocktail, PPD, anti-CD3, or SEB." (PMID 39061230, 2024). "However, data from a 2-year old calf following routine rabies and tetanus vaccination showed that both TNF-a and IL-2 responses could be successfully quantified at this age (Edwards, unpublished), suggesting that assay sensitivity may not be limiting the ability to detect immune responses." (PMID 34793450, 2021). "The production of 9 cytokines (IFN-γ, TNF-α, IL-2, IL-4, IL-10, IL-17, IL-21, TGF-β, GM-CSF) following in vitro stimulation of PBMCs with tetanus and diphtheria toxoid was analyzed, and was found to be similar in young and elderly adults." (PMID 27602049, 2016). "Catecholamines (dopamine, norepinephrine, epinephrine and total catecholamines), tumor necrosis factor (TNF)-α and LVEF were assessed during the first week of autonomic instability and following tetanus recovery." (PMID 16503969, 2006). "Heat-treated IgG (up to 57 °C) was capable of binding various antigens (tetanus toxoid (TT), diphtheria toxoid (DT) and Epstein Barr Virus nuclear antigen 1 (EBNA 1), and heat-treated IFX retained the ability to bind TNF but was somewhat less tolerant to incubation at 57 °C due to precipitation." (PMID 31199818, 2019). "Our study demonstrated that in patients with severe tetanus no significant increased levels of catecholamines or TNF-α or evidence of cardiac systolic dysfunction was observed either during autonomic instability or in the recovery period." (PMID 16503969, 2006).
alopecia (21 papers, 2014 to 2025). Hair loss usually from the scalp. "Lastly, more explanation is mandatory regarding the rare alopecia-inducing AE of TNF inhibitors in some conditions; it is crucial to halt TNF inhibitor therapy whenever such AEs appear before causing scar and irreversible baldness." (PMID 38335182, 2024). "For instance, paradoxically, TNF-α inhibitors have been reported to cause alopecia in recent years." (PMID 41470125, 2025). "Of relevance, treatment with anti-TNF-α inhibitors can also cause alopecia." (PMID 36059983, 2022). "Although it is unclear why some patients develop one manifestation rather than another, it has been suggested that the reason why only a small group of patients receiving TNF‐α inhibitors develop psoriasiform eruptions or alopecia might involve TNF receptor polymorphisms." (PMID 40944329, 2025). "It is known that tumor necrosis factor-alpha (TNFα) plays a major role in the pathogenesis of most types of alopecia." (PMID 40943437, 2025). "Our results indicated that as the severity of alopecia increased from mild to severe, there was a corresponding increase in the levels of IL-6, TNF-α, IL-17A, and IL-21." (PMID 41002719, 2025). "Interleukin-1 (IL-1) and Tumor Necrosis Factor-alpha (TNF-α) are involved in inflammatory cascades that can exacerbate alopecia." (PMID 40361941, 2025). "While drug-related alopecia was reported in adults treated with TNFα inhibitors for various indications, pediatric data are scarce." (PMID 40481366, 2025). "Literature review of pediatric TNFα inhibitor-induced alopecia revealed comparable patients’ demographics and response to treatment discontinuation." (PMID 40481366, 2025). "Our relatively large cohort provides further evidence for the need for TNFα inhibitor cessation to improve drug-induced alopecia in pediatric patients." (PMID 40481366, 2025). "Seventeen (85.0%) patients discontinued their anti-TNFα therapy due to the alopecia, all presented hair regrowth within six months." (PMID 40481366, 2025). "Further investigations revealed a significant association between serum TNF‐α levels and disease severity, as evidenced by higher TNF‐α levels in AA patients with a Severity of Alopecia Tool (SALT) score of ≥25% compared with those with a SALT score of <25%." (PMID 40260013, 2025). "The level for these biomarkers was not affected by duration or disease activity, but it was affected by the type of disease, as the concentrations of IL-15 and TNF-α were higher in patient with Alopecia totalis than in other types of Alopecia." (PMID 37206670, 2023). "The level for these biomarkers was not affected by duration or disease activity but it was affected by the types of disease as the concentration of IL-15 and TNF-α were elevated in those patients with totalis type than in other types of alopecia." (PMID 37206670, 2023). "The baseline levels of pro-inflammatory cytokines did not predict alopecia; in contrast, the concentration of IL-12, IL-2, IL-17, IFN-γ and TNF-α at 1 year was significantly increased in patients complaining alopecia." (PMID 36601115, 2022). "The pathophysiology of TNFα inhibitor-induced alopecia in not fully understood." (PMID 40481366, 2025). "Additional studies reported notable improvement with TNF-α inhibitors, indicating that these agents have largely favorable safety profiles and may serve as effective therapies for refractory scarring alopecias." (PMID 40488905, 2025). "Thus, IL-6, IL-1, and TNF-α represent a crucial set of pro-inflammatory markers that can be measured to assess alopecia’s severity and the response to PRP treatment." (PMID 40361941, 2025). "Reversible alopecia was a random AE of treatment with TNF inhibitors." (PMID 38335182, 2024). "Also, adalimumab (a TNF-α inhibitor) effectively treating a case of alopecia Universalis (a severe AA stage) prove it again that TNF-α negative regulation is effective in the treatment of AA." (PMID 34674748, 2021).
alopecia (continued). "In an alopecia model, XFZYD can significantly inhibit the levels of IL-6, IL-1β, and TNF-α in serum and skin tissue." (PMID 40430532, 2025). "Drugs targeting the tumor necrosis factor (TNF) pathway, have been explored for their potential in modulating the immune response in alopecia." (PMID 38711955, 2024). "Compared to these studies, our systematic review focused on using TNF and JAK inhibitors in treating CA, a more severe, scarring, and difficult-to-treat type of alopecia." (PMID 38335182, 2024). "Biologics, including TNF-α, IL-17, IL-23, IFNAR1 inhibitors, as well as JAK inhibitors, may represent a new frontier in the treatment of scarring alopecias refractory to the standard of care by modulating key inflammatory pathways." (PMID 40488905, 2025). "We find that TNF-α, IL-17, and JAK inhibitors may demonstrate some efficacy in managing scarring alopecias, most notably DC and FD, with some evidence for LPP, FFA, and CCCA." (PMID 40488905, 2025). "A total of 342 patients with different causes of alopecia, including LPP, FFA, EPDS, FD., DCS (PCAS), DLE, PPB, SCLE, TNF inhibitor therapy-induced CA, and some non-cicatricial subtypes (were excluded from the current review) were reported in the studies." (PMID 38335182, 2024).